TUBA4A (tubulin alpha 4a)
Diseases named in the same sentence as TUBA4A in open-access papers (continued):
Sharing a sentence is not in itself a finding about the gene and the disease.
semantic dementia (1 paper, 2022). "Exonic sequencing of the semantic dementia patient (III:2, red arrow) revealed a novel frameshift mutation c.187del (p.Arg64Glyfs*90) in exon 2 of the TUBA4A gene, which was absent in control individuals and public databases as previously published." (PMID 35327632, 2022).
tauopathies (1 paper, 2022). "Following crossbreeding with a tauopathy mouse model, the Tuba4a mutation prevented hyper-phosphorylation and oligomerization of Tau and normalized microglia activation and gliosis within the cortex, a major indicator preceding neurodegeneration." (PMID 35858909, 2022). "Strikingly, crossbreeding of Tuba4a knock-in mutants with a tauopathy model, expressing a human Tau transgene, diminishes Tau pathology and microglia activation." (PMID 35858909, 2022). "It is therefore plausible to conclude that blocking polyglutamylation at the Tuba4a C-terminus protects neuronal tissue against the consequences of reactive microglia in a tauopathy model." (PMID 35858909, 2022). "To investigate whether the Tuba4a C-terminus may be a potential target sequence in developing treatment strategies against tauopathies, we aimed to study human Tau and its tendency to form hyper-phosphorylated oligomers, in Tuba4aΔpolyGlu (p/p) mice." (PMID 35858909, 2022). "Notably, crossbreeding of the Tuba4a knock-in mouse with the hTau tauopathy model, expressing a human Tau transgene, reversed hyper-phosphorylation and oligomerization of Tau and normalized microglia activation in brain." (PMID 35858909, 2022). "Similar to the normalization of hyper-phosphorylated Tau, hTau/Tuba4aΔpolyGlu animals, lacking Tuba4a polyglutamylation revealed normalization of Tau oligomeric assemblies, as compared to hTau tauopathy mice." (PMID 35858909, 2022).
tumor (13 papers, 2018 to 2025). "In contrast, TUBA4A, a component of the microtubule cytoskeleton was involved in both of the down-regulated networks, and reduced expression of TUBA4A positively associated with poor prognosis in PC patients, suggesting a potential tumour suppressor role." (PMID 36169805, 2022). "For other genes, AURKA, PTTG1, CDC20, SLC7A5, E2F8, TPX2, and TUBA4A, high expression in the high-risk group was linked to tumour growth and metastasis." (PMID 34131308, 2021). "The relationship between miR-21, miR-17, and miR-155 and the novel MDR markers such as SEH1L, TUBA4A, and ZYX was revealed, thereby expanding the current understanding of the molecular mechanisms underlying tumor cell resistance to chemotherapy." (PMID 41463125, 2025). "It was found that high expression of ZYX, GJA1, and TUBA4A indeed correlated well with low sensitivity of tumor cells to DOX and, moreover, to another anticancer drugs, such as vincristine, topotecan, panobinostat, and cytarabine." (PMID 41153808, 2025). "Among these genes, the mRNA levels of ECT2, HNRNPK, P4HA1, and TUBA4A were significantly upregulated in the tumor tissues, when compared to those in normal tissues." (PMID 35284334, 2021). "In addition, we found that FAM107B expression was remarkably downregulated while TUBA4A expression was remarkably upregulated in tumor group in comparison with normal group." (PMID 37861558, 2023). "The 6-protein diagnostic panel consisted of FLNA, PRDX6 and ARHGDIB, associated with tumor growth, cell invasion and metastasis, GSTO1, having an antioxidant defense role (together with PRDX6), TUBA4A, found enriched in serum exosomes from NSCLC patients, and the tumor suppressor CDH13." (PMID 32575471, 2020). "The first tumor-reactive subcluster, resident memory T cells (TRM), was characterized by specific expression of NR4A2, NR4A3, and TUBA4A, undertaking immune surveillance and immune activation." (PMID 40315321, 2025). "To address this issue, we calculated hazard ratio (HR) values for SEH1L, TUBA4A, TCF3, ZYX, and GJA1, both individually and in combination, using tumor data from The Cancer Genome Atlas (TCGA)." (PMID 41153808, 2025). "The protein levels of DDIT4, TUBA4A, and PTTG1 were markedly elevated in tumor tissues, whereas SLA and BTG2 were notably diminished compared to normal tissues." (PMID 38200058, 2024). "We discovered that the protein levels of HNRNPK, P4HA1, and TUBA4A were significantly upregulated, while CTSL, HNRNPK, and OSBPL5 were significantly downregulated in the tumor tissues compared to those of normal tissues." (PMID 35284334, 2021). "NEK2 was altered in 22.9% of analyzed tumor samples and found interacted with the α-tubulin isoforms TUBA1A, TUBA4A, the β-tubulin isoforms TUBB, TUBB4A, TUBB4B and all the γ-tubulin isoforms." (PMID 30126203, 2018). "Additionally, the protein expression levels of SLA, BTG2, DDIT4, TUBA4A, and PTTG1 in LUAD tumor tissues and normal tissues were investigated using the Human Protein Atlas (HPA) database." (PMID 38200058, 2024).
neurodegenerative disease (7 papers, 2022 to 2025). A disorder of the central nervous system characterized by gradual and progressive loss of neural tissue and neurologic function. "This could explain why TUBA4A dysregulation may contribute to adult-onset neurodegenerative disease, contrary to mutations in other tubulin isotypes involved in neurodevelopmental disorders." (PMID 38463699, 2024). "TUBA4A encodes tubulin alpha-4A, which has been associated with various neurodegenerative diseases, but has not been described yet as a MDR-associated gene." (PMID 41153808, 2025).
cancer (5 papers, 2020 to 2025). A tumor composed of atypical neoplastic, often pleomorphic cells that invade other tissues. "The limited prior association of SEH1L, TUBA4A, ZYX, and TCF3 with chemoresistance, combined with their consistent dysregulation across cancer types, nominates them as novel and promising biomarker candidates for predicting DOX sensitivity." (PMID 41153808, 2025). "Downregulation of TLN1, ITGB3, and TUBA4A with simultaneous upregulation of HSPG2 protein were observed in cancer samples compared to healthy controls." (PMID 37241967, 2023). "According to the database annotation, universal EV proteins (CDC42, GNAI2, ITGB3, TLN1, and TUBA4A) are involved in platelet activation that help cancer cells escape immune surveillance and provide a prometastatic microenvironment." (PMID 32916986, 2020). "Our findings indicated that the interactions between CD8T cells and other cellular components play a significant role in certain cancer-related signal pathways, and the mutations of FAM107B and TUBA4A were not important factors in the development of PTC." (PMID 37861558, 2023).
infection (4 papers, 2021 to 2025). The state of being infected such as from the introduction of a foreign agent such as serum, vaccine, antigenic substance or organism. "Similarly, a number of genes placed in “Axonal guidance”, including several modulated by infection (SLIT2, PLCD1, SLIT-ROBO Rho GTPase-activating protein 2 (SRGAP2) and TUBA4A), showed elevated expression." (PMID 37276213, 2023).
myopathies (2 papers, 2025 to 2026). "In conclusion, this study establishes that missense variants in TUBA4A can cause myopathy and multisystem proteinopathy with variable clinical and histopathological features, including p62 accumulation, internal nucleation, autophagy dysfunction, and myofibrillar disarray." (PMID 40666348, 2025). "Together, these results underscore the importance of including TUBA4A in genetic screening panels for unresolved myopathies and related neuromuscular conditions." (PMID 40666348, 2025). "Through in silico, in vitro, histopathological and immunohistochemical analyses, we characterise the phenotypic and molecular spectrum of TUBA4A-related myopathies and multisystem proteinopathies – henceforth referred to as ‘myo-tubulinopathies’." (PMID 40666348, 2025).
TUBA4A also shares sentences with these, for which no sentence is quoted: Lissencephaly (4 papers); neurodevelopmental disorder (4); cognitive decline (2); dementia (2); neurological diseases (2); adenocarcinoma (1); autosomal dominant spastic ataxia (1); cerebellar ataxia (1); Charcot-Marie-Tooth disease (1); Cognitive impairment (1); congenital myopathy (1); cyst (1); dilated cardiomyopathy (1); epilepsy (1); Epstein-Barr virus infection (1); familial amyotrophic lateral sclerosis (1); hereditary spastic paraplegia (1); Insulin resistance (1); lipodystrophy (1); liposarcoma (1); lung adenocarcinoma (1); Macrocephaly (1); metastatic tumors (1); muscular dystrophy (1); neuromuscular disease (1); ovarian carcinoma (1); peripheral neuropathy (1); primary progressive aphasia (1); ptosis (1); Salmonella Infections (1).
A further 5 diseases each share a sentence with TUBA4A in 1 paper.